EGFR (epidermal growth factor receptor)
Diseases named in the same sentence as EGFR in open-access papers (continued):
Sharing a sentence is not in itself a finding about the gene and the disease.
tumor (16,486 papers, 1987 to 2026). "In NSCLC tissue, the EGFR mutation VAF reflects tumor clonality and intratumoral heterogeneity, and accumulating evidence suggests an association between EGFR VAF and response to EGFR-targeted TKIs." (PMID 42201025, 2026). "In summary, this study demonstrates that low-dose EGFR targeting creates a susceptible state for ferroptosis in tumor cells and, consequently, defines a combination therapy strategy of EGFR-targeted agents with chemotherapy for TNBC." (PMID 42190815, 2026). "Small molecule inhibitors targeting EGFR can effectively slow the progression of disease, and in some settings, these drugs even cause dramatic tumor regression." (PMID 41932441, 2026). "By focusing on CD73‐adenosine axis and dysfunctional DCs, our study provides novel insights into how EGFR mutations reshape the TME to suppress the effective anti‐tumor immunity." (PMID 41144813, 2026). "Aberrant activation of the Hippo pathway effector Yes-associated protein (YAP) and its crosstalk with epidermal growth factor receptor (EGFR) signaling have been implicated in tumor progression, cancer stemness, and metastasis." (PMID 42158813, 2026). "We performed a comprehensive, cross-cohort analysis of BRAF, KRAS, and EGFR mutation subtypes using 64,807 cBioPortal tumor samples, 1570 cancer cell lines, and 2714 Belgian clinical cases." (PMID 42253180, 2026). "This loss results in diminished inhibition of EGFR/ERK signaling in tumor cells, thereby promoting EMT and metastasis." (PMID 41511367, 2026). "Four risk factors were incorporated into a weighted risk index-high-grade patterns ratio, epidermal growth factor receptor mutation status, spread through air spaces status and consolidation tumor ratio-to establish the "CEHS" RFS prediction model." (PMID 42023991, 2026). "Mechanistic studies revealed that tumor-derived ANG binds epidermal growth factor receptor (EGFR) on tumor-associated macrophages (TAMs), activating RhoA-dependent cytoskeletal remodeling and autocrine ALK5/TGFβ signaling." (PMID 41975075, 2026). "For EGFR Mut LUAD patients, the emergence of drug-resistant EGFR mutations through tumor evolution and selective pressure from therapeutic interventions underscores the critical need for novel EGFR-targeting agents with alternative inhibitory mechanisms." (PMID 41522352, 2026). "This group typically exhibits a higher frequency of EGFR mutations and different tumor microenvironment features." (PMID 41601672, 2026). "This study aimed to determine the incidence, characteristics, severity, and duration of the first AEs and to evaluate their association with tumor response in patients with NSCLC receiving EGFR-TKIs." (PMID 41899369, 2026). "Amivantamab and lazertinib act synergistically against EGFR pathologic activity, producing therapeutic effects in patients whose tumours harbour EGFR-activating mutations." (PMID 41590374, 2026). "EGFR-mutant tumors exhibit unique immunogenicity compared to wild-type tumors, with heterogeneity in programmed death ligand 1(PD-L1) expression levels, tumor mutational burden (TMB), and other immune microenvironment characteristics." (PMID 42317338, 2026). "Oncogenic mutations within the tyrosine kinase (TK) domain of EGFR play a critical role in activating downstream signaling pathways that promote tumor growth and survival." (PMID 41799114, 2026).
tumor (continued). "EGFR-mutated NSCLC is characterized by a well-defined tumor immune microenvironment (TIME) that is generally less immunogenic and more immunosuppressive compared to EGFR wild-type counterparts." (PMID 41357575, 2025). "In this study, both artificial mixed samples containing 1‰ of 1 of 3 EGFR gene mutations (L747_S752 del, G719A, and T790M) and tumor samples were used to evaluate the feasibility of the proposed new method." (PMID 40587690, 2025). "For example, NSCLC patients with EGFR mutations are highly sensitive to EGFR‐TKIs, with significant tumor shrinkage observed early in treatment." (PMID 40959866, 2025). "Among the key drivers of OSCC progression, the overexpression of epidermal growth factor receptor (EGFR) has been strongly linked to enhanced tumor growth, invasion, and resistance to therapy." (PMID 40472740, 2025). "Currently, the gold standard for determining EGFR mutation status is molecular testing of tumor tissue obtained through needle biopsy or surgical resection." (PMID 41263395, 2025). "Due to the unavailability of tumor tissues, polymerase chain reaction (PCR)-based epidermal growth factor receptor (EGFR) mutation analysis was performed using pleural fluid samples." (PMID 40678598, 2025). "EGFR mutations, especially in exons 19 and 21, are associated with tumor proliferation and responsiveness to tyrosine kinase inhibitors, making EGFR of therapeutic and prognostic relevance in SMs from NSCLC." (PMID 40868304, 2025). "Previous studies have reported that plasma ctDNA levels are correlated with tumor and metastatic burdens and that the loss of detectable ctDNA early in EGFR-TKI treatment is associated with favorable clinical outcomes." (PMID 39317868, 2025). "MUC1 glycan isomerization has been implicated in altering EGFR recycling and promoting immune evasion, thereby contributing to the development of a drug-resistant tumor microenvironment." (PMID 41020875, 2025). "The authors concluded that both afatinib and osimertinib exhibit favorable tumor responses in NSCLC patients harboring uncommon EGFR mutations." (PMID 40364160, 2025). "Overactivation of EGFR has been linked to enhanced tumor cell survival, proliferation, and migration, making EGFR-targeted therapies a valuable approach in NSCLC treatment." (PMID 41155558, 2025). "Following the success of ADAURA in EGFR-mutated tumours, the phase III ALINA trial evaluated 2 years of adjuvant alectinib versus standard PBC in patients with ALK-rearranged stage IB-IIIA (TNM7) resected NSCLC." (PMID 40628491, 2025). "A small prospective study (n=21) indicated that the detection rate of EGFR mutations in CSF circulating tumor DNA (ctDNA) was about 2.4 times higher than that in blood." (PMID 39949743, 2025). "In EAC, EGFR has been found to be highly expressed and its expression to be associated with increased tumor invasion (pT)." (PMID 39795613, 2025). "In contrast, tumor mutational status, particularly mutations in driver genes such as EGFR, KRAS, and STK11, has recently emerged as a more stable predictor of immunotherapy response." (PMID 40777022, 2025). "One of the oncogenic effectors associated with Cdc42 is PI3K, and the Akt signaling pathway activated by the EGFR-Cdc42 is significantly linked to tumor recurrence and resistance." (PMID 40634295, 2025). "The analysis identified smoking history (P = 0.012), λHU (P = 0.015), and tumor surface area (P = 0.029) as independent predictors of EGFR mutations, retaining statistical significance in the final model." (PMID 41244899, 2025). "In contrast, specimens obtained via FNA exhibit disrupted tissue architecture and reduced tumor cellularity and thus pose a distinct challenge for EGFR mutation prediction." (PMID 41211715, 2025). "What stands out is that these pan-tumour drugs are also amenable to targeted therapy for mutations like EGFR and ALK." (PMID 39212880, 2025).
tumor (continued). "In mice with NSCLC cells harboring EGFR mutations, the combination of the anti-PD-L1 antibody durvalumab and oleclumab significantly decreased tumor volume." (PMID 41188606, 2025). "EGFR mutations suppress the tumor immune microenvironment by interfering with multiple intracellular pathways and regulating immune helper cells." (PMID 40181972, 2025). "Various methods are used to detect EGFR mutations in tumours and blood, including polymerase chain reaction (PCR)‐based, mass spectrometry‐based, and next‐generation sequencing (NGS)‐based techniques." (PMID 40515576, 2025). "Its overexpression and amplification are linked to tumor progression, and anti-EGFR therapies such as cetuximab are being tested for advanced HNSCC." (PMID 41463200, 2025). "In South Korea, lazertinib monotherapy was approved in 2021 for the treatment of patients with the EGFR T790M mutation in tumor tissues or plasma after unsuccessful treatment with either first‐ or second‐generation TKI agents." (PMID 40396522, 2025). "Genetic events like mutations in PIK3CA, TERT alterations, and EGFR amplifications found in the primary tumor typically persist in the recurrent tumor." (PMID 40141375, 2025). "Summary of studies evaluating the association between serum tumor markers and EGFR molecular status." (PMID 40977812, 2025). "It systematically evaluates the results of studies targeting key tumor-associated antigens, such as EGFR, IL13Rα2, GD2, B7-H3, CEA, MSLN, PSCA/PSMA, and ROR1." (PMID 40969260, 2025). "Prominently, elevated levels of a variety of transcription factors linked with tumor progression, such as EGFR, FOXM1, STAT3, FGFR1, and GATA6, were identified in the high PANO subtype." (PMID 40918470, 2025). "Elevated SPINK 1 expression is associated with aggressive tumor behavior and unfavourable prognosis, often functioning as an oncogene that enhances EGFR activation and downstream signalling." (PMID 40872585, 2025). "In vivo, H1975 and PC-9 xenograft models with EGFR-sensitive mutations were used to assess the effects of IL-35 on tumor growth and NK-cell infiltration." (PMID 41357575, 2025). "In univariate analysis, tumor surface area was significantly greater in the EGFR mutation group than in the wild-type group (P = 0.043), while other AI-derived parameters showed no statistical significance." (PMID 41244899, 2025). "Progesterone has been shown to inhibit tumor growth via the PR, while AR expression has been associated with the response to EGFR-TKI therapy." (PMID 40868244, 2025). "Our in vitro and in vivo results show that the bispecific B10–B11 Nanofitin efficiently inhibits immune checkpoints through co-engagement of two tumor-associated antigens, EGFR and PD-L1." (PMID 40305184, 2025). "Prior to surgery, these outputs can be reviewed at the multidisciplinary tumour board in conjunction with molecular data (e.g., EGFR amplification) to stratify language risk and plan the surgical strategy." (PMID 40941753, 2025). "Although VA-ECMO is generally considered a relative contraindication in patients with end-stage malignancy, the tumor in this case harbored a deletion mutation in exon 19 of EGFR, which is known to respond rapidly to the molecularly targeted agent osimertinib." (PMID 41348429, 2025). "indicates that smoke exposure can induce differentiation of Ly6G + MDSCs into tumor-associated macrophages (TAMs), which secrete epidermal growth factor receptor (EGFR) ligands to accelerate PanIN development in the KC mouse model." (PMID 40104059, 2025). "Specifically, when μNMR is combined with multiple tumor markers like EGFR, EGFRvIII, PDPN, and IDH1-R132H, the overall diagnostic accuracy has been elevated to over 90%." (PMID 39465690, 2025). "In another study, two AI modules managed to identify EGFR status in a chest CT tumor with AUC of 0.842 and 0.928, respectively, while one of them achieved an AUC of 0.805 in mutated-EGFR sub-type discrimination (19Del, L858R, other mutations)." (PMID 40075729, 2025).
tumor (continued). "A prior case report revealed that osimertinib, bevacizumab, and brigatinib combination treatment relieved tumor growth and respiratory symptoms in a patient with adenocarcinoma harboring an EGFR L858R/T790M/C797S triple mutation." (PMID 40422529, 2025). "An additional potential anti-tumor mechanism associated with MSCs is their influence on epidermal growth factor receptor (EGFR) signaling." (PMID 39974358, 2025). "Potential explanations for the observed discrepancy in the EGFR rate in our study include demographic and geographic differences, the EGFR variant found, tumor source (primary or metastatic), and the testing method performed." (PMID 40422533, 2025). "We report how cerebrospinal fluid (CSF) circulating tumor DNA (ctDNA) clarified therapeutic direction in EGFR-mutated non-small-cell lung cancer (NSCLC) with leptomeningeal involvement." (PMID 41446706, 2025). "The second possibility is “mutational switching,” where one EGFR mutation replaces another upon tumor recurrence." (PMID 40197845, 2025). "Chromosomal instability, such as EGFR amplification and combined chromosome 7 gain/chromosome 10 loss, also plays a significant role in tumor progression and treatment response." (PMID 40542948, 2025). "EGFR dysregulation, particularly amplifications and point deletions, has been implicated in enhancing tumor invasion and resistance to radiation and chemotherapy." (PMID 41212363, 2025). "Other targeted therapies, such as cetuximab, a monoclonal antibody that inhibits EGFR, appear to be associated with tumor growth inhibition." (PMID 40723400, 2025). "High IL-35 expressions associated with larger tumor size (χ2 = 16.140, P = 0.000) and EGFR mutation status (χ2 = 4.843, P = 0.028)." (PMID 41357575, 2025). "For example, one report described sustained tumor shrinkage and long-term survival in a patient with concurrent EGFR mutation and HER2 amplification who was treated with a combination of osimertinib and pyrotinib." (PMID 41426315, 2025). "Multivariate logistic regression indicated that age, GGOs types, tumor diameter and pathological types were significant predictors for EGFR mutations status." (PMID 39833382, 2025). "Several variants of EGFR-targeting affibodies demonstrated higher tumor uptake (range between 2.7 and 8.6%ID/g at 3 h after injection), and tumor-to-blood ratios were also higher for these tracers (range between 7 and 12)." (PMID 41226646, 2025). "Recent investigations further suggest that reduced tumor long-axis diameter correlates with increased EGFR mutation risk, while ground-glass opacity patterns are strongly linked to EGFR-mutant tumors." (PMID 40708937, 2025). "CT features like the air bronchogram, spicule sign, and tumor size have been linked to EGFR mutations." (PMID 41378298, 2025). "In summary, we have unveiled the pivotal role and underlying mechanism of EGFR in promoting tumor angiogenesis by controlling the PCBP2-dependent miRNA sorting into sEVs." (PMID 39816681, 2025). "Activation of the epidermal growth factor receptor (EGFR) stabilizes β-catenin in tumor cells coexpressing fascin, an actin-binding protein linked to adhesion, migration, invasion, and cytoskeletal reorganization." (PMID 40433410, 2025). "The initial approval was for the treatment of patients with metastatic NSCLC whose tumours have specific EGFR mutations, specifically T790M mutations, and whose disease has progressed on or after EGFR TKI therapy." (PMID 39858093, 2025). "The results of GO and KEGG analyses demonstrated that the high-frequency mutations were notably concentrated in the PI3K-Akt signaling pathway and pathways associated with EGFR kinase inhibitor resistance, which are closely implicated in tumor development." (PMID 39744567, 2025).
tumor (continued). "Numerous studies have shown that mutations and abnormal activation of EGFR are closely related to tumour progression and treatment resistance in various epithelial malignancies." (PMID 39910656, 2025). "Lastly, future studies should further investigate the relationship between tumor heterogeneity in brain tissue and EGFR-TKI treatment response, aiming to explore the underlying biological mechanisms and enhance the interpretability of radiomics models." (PMID 40438144, 2025). "A systematic review and meta-analysis demonstrated that EGFR overexpression was significantly associated with poorer overall survival, increased likelihood of lymph node metastasis, and poor tumor differentiation in patients with OSCC." (PMID 40699851, 2025). "Second, while our study provides evidence of associations between ADAM9 SNPs, tumor size, and EGFR mutation frequency in LUAD patients, we lack survival data for the recruited cohort." (PMID 40429751, 2025). "In the ‘Drug Resistance: Anti-tumor Drugs’ module, it was found that C1 were associated with ‘EGFR tyrosine kinase inhibitor resistance’, which aligns with their intrinsic or early resistance to targeted EGFR inhibition." (PMID 40948762, 2025). "Its activating mutations are associated with aggressive tumor behavior and resistance to certain therapies, including anti-EGFR treatments in colorectal cancer." (PMID 40940900, 2025). "The results of a clinical study showed that poziotinib effectively controlled tumor growth in patients with EGFR exon 20 insertion mutations." (PMID 41472727, 2025). "Despite harbouring a targetable mutation, the tumour showed poor response to EGFR‐TKI, highlighting the challenges of managing aggressive tumours with coexisting airway fungal infection." (PMID 40395487, 2025). "Changes in the tumor microenvironment after EGFR mutation are closely related to tumor progression and treatment efficacy." (PMID 40181972, 2025). "The efficacy of pembrolizumab in TKI-naïve advanced NSCLC patients with EGFR mutations and high PD-L1 tumour expression was evaluated in a phase II clinical trial." (PMID 40647497, 2025). "PIT associated with ASP-1929, which targets EGFR expressed on the surface of HNSCC tumor cells, has proven its effectiveness in rapidly destroying tumor tissue in preclinical and recent clinical studies." (PMID 40574027, 2025). "Clinical variables assessed included demographic data, comorbidities, Eastern Cooperative Oncology Group (ECOG) performance status, tumor characteristics, genetic mutations (EGFR, ALK, ROS1), treatment responses, toxicity profiles, and survival outcomes." (PMID 40805843, 2025). "Circulating tumour DNA analyses tracking 467 somatic variants revealed the presence of this EGFR wild-type clone before vaccination and its expansion during osimertinib/NPV therapy." (PMID 39972134, 2025). "This interaction reduces EGFR degradation, resulting in sustained EGFR pathway activation, which is implicated in tumor progression." (PMID 40906372, 2025). "The tumor mutation burden (TMB), PD-L1, and tumor immune cell infiltrations were also analyzed across these EGFR mutation subtypes, to explore the potential underlying mechanisms." (PMID 41162774, 2025). "In this study, we showed that CMTM4 regulated tumor growth by modulating tumor-associated inflammation and leukocyte infiltration related to EGFR expression, trafficking, and activation." (PMID 39948411, 2025). "Substantial evidence indicates that tumors with EGFR mutations promote immune escape by upregulating PD-1, PD-L1, and other tumor-promoting inflammatory cytokines." (PMID 40936915, 2025). "Several previous studies have investigated the correlation between the efficacy of osimertinib and the EGFR-mutated circulating tumor (ct) DNA level in T790M-mutated patients receiving osimertinib therapy." (PMID 39317868, 2025). "EGFR amplification has been associated with increased tumor proliferation, invasiveness, and radioresistance." (PMID 40722305, 2025).